BCL2 (BCL2 apoptosis regulator)
Diseases named in the same sentence as BCL2 in open-access papers (continued):
Sharing a sentence is not in itself a finding about the gene and the disease.
diabetes (continued). "To explore the possible role of reductive stress in diabetes and myocardial IR injury, we thus determined several defense antioxidants including BAG3, Bcl-2, Nrf-2 and HO-1 expression of the heart in response to diabetes and myocardial IR injury." (PMID 32751309, 2020). "Western blot analysis showed that diabetes dampened phosphorylation of AKT and GSK3β, p-AKT-to-AKT ratio and p-GSK3β-to-GSK3β ratio, and enhanced expression of Bax, Bcl-2, cleaved caspase-3 and TGF-β, which was mitigated in the cathepsin K knockout." (PMID 28821796, 2017). "Diabetes significantly increased myocardial CHOP expression (P < 0.05), ratio of Bax/Bcl‐2 (P < 0.05) and caspase‐3 activity (P < 0.05)." (PMID 27957794, 2017). "A recent study reported that the dissociation of Bcl-2 from Beclin1 via activated AMPK enhances cardiac autophagy and protects against cardiomyocytes in diabetes." (PMID 28421194, 2017). "BRD7 inhibition effectively ameliorated diabetes‐induced CHOP expression (P < 0.05), ratio of Bax/Bcl‐2 (P < 0.05) and caspase‐3 activity (P < 0.05)." (PMID 27957794, 2017). "Western blot analyses revealed higher levels of both C-caspase 3 and Bax in the diabetes + SCI group relative to the SCI group, whereas expression of Bcl2 declined." (PMID 26597839, 2015). "An obvious increasing of testicular apoptosis in diabetic rats at 2 months after diabetes onset, measured by TUNEL staining, was found along with a significant increase in Bcl-2/Bax ratio." (PMID 25861655, 2015). "Sitagliptin treatment showed an antiapoptotic effect since it was able to prevent the diabetes-induced increment of mRNA and protein BAX/Bcl-2 ratio." (PMID 24817793, 2014). "Curcumin was antidiabetic therapy, induced hypoglycemia by up-regulation of IGF-1 gene and ameliorate the diabetes induced oxidative stress via increasing the availability of GSH, increasing the activities and gene expression of antioxidant enzymes and Bcl2." (PMID 24364912, 2013). "Diabetes decreased p308-Akt, p473-Akt, p136-BAD, Bcl-2 expression and Bax/Bcl-2 ratio, increased the expression of Bax as compared with the non-diabetic group." (PMID 22432030, 2012). "Additionally, the three disease targets with the highest connectivity values in the string network, STAT3, BCL2, and AKT1, also mediate multiple diabetes-related signaling pathways and are key targets in the treatment of diabetes." (PMID 40733369, 2025). "Experimental results have shown that streptozotocin-induced diabetes could significantly increase levels of TUNEL(+) cells, activated caspase-3, Bax, Bax/Bcl2, and cytochrome c in the hippocampus and cerebral cortex." (PMID 35743182, 2022). "Three of these coding genes (BCL2, HIF1A, and TIMP3) were common genes in diabetes and DR." (PMID 34707685, 2021). "Simultaneously, chronic HPTQ treatment debilitated diabetes-induced cognitive deficits and regulated hippocampal insulin metabolism activated CREB/BDNF/TrkB signaling pathway and suppressed the mitochondria-related Bax/Bcl-2 and caspase-3 apoptosis pathway." (PMID 34211563, 2021). "Finally, our study explored the response of the cardiac endogenous defense mechanism in BAG3/Bcl-2/Nrf-2/HO-1 and NADPH oxidase p22/p67-mediated oxidative stress in response to diabetes and myocardial IR injury." (PMID 32751309, 2020). "However, diabetes inhibits the AMPK activity, suppresses its JNK1-BCL2 cascade, and promotes the interaction between Beclin1 and BCL2." (PMID 29204251, 2017).
diabetes (continued). "Another research also reported that diabetes induced apoptosis and suppressed autophagy of cardiomyocytes through inhibiting AMPK, suppressing the MAPK8/JNK1-Bcl-2 signaling pathway, and subsequently promoting the interaction between Beclin-1 and Bcl-2." (PMID 26950124, 2016). "Further increases in both C-caspase 3 and Bax were detected in the diabetes + SCI groups relative to the SCI group 7 days after contusion (P < 0.05); the reverse was seen for Bcl2, with progressively lower levels seen in the SCI and diabetes + SCI groups relative to controls (P < 0.05)." (PMID 26597839, 2015). "Expression of apoptosis-related marker such as Bcl-2 gives the new mean of regulating the apoptosis pattern in diabetic and nondiabetic wound healing of rat model of diabetes." (PMID 24223310, 2013). "Furthermore, the effect of curcumin on gene expression of Bcl-2 and IGF-1 in streptozotocin-induced diabetes in rats was also determined." (PMID 24364912, 2013). "Unlike the increment in the expression of proapoptotic gene (Bax) by the induction of diabetes in D group, the expression of antiapoptotic Bcl-2 gene neither altered by inducing of diabetes (in group D) nor by the treatment of the diabetic rats with curcumin or metformin." (PMID 35935389, 2022). "When diabetes rats were pretreated with low concentration of EtOH, which was used as a tool to induce ALDH2 activity, LDH level was decreased; whereas LVDP, ±dp/dtmax, RP, SOD activity and Bcl-2 mRNA level were increased, MDA content and Bax mRNA level were decreased." (PMID 27829984, 2016). "Furthermore, transgenic expression of the anti-apoptotic protein Bcl-2 does not prevent losses in pancreatic β-cell mass in animals with autoimmune forms of diabetes." (PMID 21829464, 2011). "As a result, the onset and incidence of diabetes in three mouse models of T1D—multiple low-dose streptozotocin-induced diabetes, RIP-B7-1 mice, and non-obese diabetic (NOD) mice—were similar between wild-type and transgenic mice overexpressing Bcl-2." (PMID 39857806, 2025). "Compared to the diabetes group, early and late DMEM administrations did not affect the gene expression levels of Bax, Bcl-2, and TNF-ɑ." (PMID 39391856, 2024). "DMEM treatment did not affect the gene expression level of Bax, Bcl-2, BDNF, and TNF-ɑ compared to the diabetes group." (PMID 37081849, 2023). "Bcl-2 inhibitors, including ABT199 (venetoclax), eliminated senescent β cells and reduced the incidence of diabetes in non-obese diabetic (NOD) mice." (PMID 35432205, 2022). "Indeed, in non-obese diabetic mice, treatment with anti-Bcl-2 inhibitors, such as ABT199, eliminates senescent pancreatic β cells, resulting in prevention of diabetes mellitus." (PMID 35432205, 2022). "Interestingly, the pharmacological inhibition of Bcl-2 by the ABT-737 Bcl-2/Bcl-xL inhibitor or the Bcl-2-specific inhibitor ABT-199 eliminated senescent β-cells in NOD mice, preventing diabetes development in this model without affecting the immune cell population or non-senescent β-cells." (PMID 39857806, 2025). "It is possible, that the milder diabetes that develops in obese VDF rats, when compared to obese ZDF rats, is due to a more robust anti-apoptotic response, since the latter exhibit reduced β-cell bcl-2 levels, although we have no direct evidence to support this suggestion." (PMID 20231880, 2010).
Sepsis (153 papers, 2007 to 2026). Sepsis is defined as life-threatening organ dysfunction caused by a dysregulated host response to infection. "Previous investigations documented CLM's anti-apoptotic effect through stimulating Bcl-2 and suppressing Bax in cardiac damage caused by sepsis and myocardial ischemia–reperfusion Injury." (PMID 40770673, 2025). "In this context, Bcl-2 overexpression in immune cells has been shown to protect against sepsis-associated apoptosis, improving survival by up to threefold compared to controls." (PMID 40564127, 2025). "Overexpression of B-cell lymphoma 2 (BcL-2), an anti-apoptotic protein, has been observed following decreased cell death in gut epithelia and has been associated with better survival rates in sepsis mice." (PMID 38254870, 2024). "The staining of BCL-2 in the spiral ligament was highest in sepsis mice with low hearing loss (4.02)." (PMID 28404559, 2017). "In the sepsis mice with low hearing loss the staining intensity of BCL-2 was nearly the same as in the mice with high hearing loss." (PMID 28404559, 2017). "In the sepsis mice with high hearing loss we found a staining of BCL-2 in the spiral ganglion cells." (PMID 28404559, 2017). "This appears to be physiologically significant since overexpression of Bcl-2 is associated with increased survival from sepsis from either P. aeruginosa or cecal ligation and puncture (CLP)." (PMID 25010671, 2014). "First, because Gas6, via Akt, causes an increase in the antiapoptotic protein Bcl-2, it is tempting to link the delayed neutrophil apoptosis observed during sepsis with the concentration of this protein." (PMID 17241453, 2007). "CLM mitigated cardiac dysfunction caused by sepsis via regulating the Bax and Bcl-2 signals." (PMID 40770673, 2025). "Furthermore, silencing miRNA‐195 by gene KO can increase the expression of certain proteins—BCL‐2, Sirt1 and Pim‐1—and significantly reduce the potential trans‐organ damage associated with sepsis." (PMID 38014923, 2024). "The current study indicated that the development of SIMI may be associated with the activation of Bax and the inhibition of Bcl-2, resulting in apoptosis in cardiomyocytes during sepsis." (PMID 38161332, 2023). "To determine whether SDF-1-pretreated ERCs could further reduce the damages caused by sepsis at the molecular level, we examined the mRNA levels of apoptosis-related genes Bcl-2 and Bax in liver to evaluate apoptosis." (PMID 32256608, 2020). "The antiapoptotic marker BCL-2 showed a slight upregulation in the sepsis mice with low hearing loss, although also in the sham mice a basal expression level could be observed." (PMID 28404559, 2017). "Furthermore, a serious mechanism researches reveal inhibiting gut epithelial apoptosis by overexpression of Bcl-2 was associated with a survival advantage in pseudomonas pneumonia-induced sepsis." (PMID 27682607, 2016). "Earlier, we reported that a progressive decline in myocardial performance at 3 and 7 days in a hyperdynamic model of sepsis is associated with increased levels of proapototic caspase-3, increased B-cell leukemia (Bcl2)-associated protein×(Bax)/Bcl2 ratio and release of cytochrome C." (PMID 21712982, 2011). "The combination of an increase of Bim, Bid and Bad in conjunction with lowered levels of Bcl-2 and Bcl-xl may render cells more susceptible to apoptosis during sepsis." (PMID 18925930, 2008). "The sepsis group exhibited markedly higher pro-apoptotic Bax and lower anti-apoptotic Bcl-2 levels in kidney tissues than the untreated control group (P < 0.05)." (PMID 41585603, 2026).
Sepsis (continued). "Intervention with L-carvone at all three doses resulted in markedly lower Bax and higher Bcl-2 renal levels than observed in the sepsis model (P < 0.05)." (PMID 41585603, 2026). "Strategies to reduce apoptosis, such as the overexpression of anti-apoptotic proteins such as Bcl-2 in the gut epithelium, have demonstrated protective effects in pre-clinical sepsis models." (PMID 40098052, 2025). "This is supported by our findings that the expression pattern of AKT1 was consistent with that of BCL2 in both sepsis and COVID-19." (PMID 41411324, 2025). "Apoptosis is dramatically promoted during sepsis because of the elevated expression of the Bax/Bcl-2 ratio." (PMID 40770673, 2025). "This is in line with our results that revealed the decreased Bcl-2 gene expression, whereas the upregulated Bax and caspase-3 genes expression after sepsis induction." (PMID 40770673, 2025). "lncRNA HOTAIR has been reported to mediate severe organ injury in a sepsis rat model through the miR-34a/Bcl-2 axis." (PMID 39067063, 2025). "For example, animal models have shown that the overexpression of BCL-2 or caspase inhibition to prevent apoptosis improves survival in sepsis." (PMID 40564127, 2025). "The volcano plot and heatmap indicated that JAK3, CHMP5 and IFNAR1 were upregulated while CASP8, VDAC2, FASLG, JAK1, STAT4 and BCL2 were downregulated in sepsis." (PMID 38894720, 2024). "Bcl-2, a key anti-apoptotic protein, helps maintain cellular integrity, and its downregulation, as often seen in sepsis, can amplify apoptosis, contributing to organ dysfunction." (PMID 38546748, 2024). "miR-7-5p, which is also found to be upregulated in plasma exosomes in patients with sepsis, regulates the expression of the antiapoptotic gene Bcl-2, inhibiting T lymphocyte apoptosis and thus mitigating sepsis damage." (PMID 39104595, 2024). "Previous publications reported that BCL2 was upregulated in the kidney tissue in LPS-induced sepsis while downregulated in the heart in ischemia-reperfusion model." (PMID 38894720, 2024). "Following anti-NGF treatment 24 h after sepsis induction, Bcl-2 expression increased, and Bax expression decreased in mouse tissue, resulting in a reduction of apoptosis." (PMID 38313013, 2024). "Remarkably, treatment with resveratrol (CLP + RV group) and resveratrol-loaded silver nanoparticles (CLP + AgNPs-RV group) led to a marked resurgence in Bcl-2 levels, suggesting a potential protective effect against sepsis-induced apoptosis." (PMID 38546748, 2024). "In summary, we systematically identified 11 apoptosis-related differentially expressed genes in sepsis, and four hub genes (BCL2, FASLG, JAK3 and IRF9) were recognized as valuable diagnostic biomarkers." (PMID 38894720, 2024). "Markers like Bcl-2 and Caspase-3 offer a window into the apoptotic processes activated during sepsis." (PMID 38546748, 2024). "More interestingly, in the current work, Gabapentin treatment significantly decreased the expression of the Bax gene and markedly elevated the expression of the Bcl-2 gene, showing its renal anti-apoptotic efficacy during sepsis induced by CLP." (PMID 37548662, 2024). "It has been reported that Bcl-2 (an anti-apoptotic protein) overexpression mitigates sepsis-induced hyperpermeability by altering tight junctions in a mouse model of CLP-induced sepsis." (PMID 39769181, 2024). "These treatments prompted a remarkable recovery in Bcl-2 levels, suggestive of their potential to confer protection against sepsis-induced apoptosis." (PMID 38546748, 2024). "In the study, we found that 4 necroptosis-related hub genes (BACH2, GATA3, LEF1, and BCL2) were closely related to sepsis, providing a potential new target for the diagnosis and therapy of sepsis." (PMID 37091800, 2023). "Increased expression of anti-apoptotic protein Bcl-2 provides septic protection and improved survival in experimental sepsis-CLP." (PMID 37407986, 2023).
Sepsis (continued). "The expression of apoptotic genes was different from the previous indicators: LPS-induced sepsis decreased Bcl-2 expression, increased Bax expression, and increased apoptosis." (PMID 37434129, 2023). "In vivo studies have proven the cardioprotective role of anti-apoptosis during sepsis and highlighted the engagement of Bax, Bcl-2, Bcl-xl, Caspase 3, and Caspase 9 in sepsis-induced cardiomyocyte apoptosis." (PMID 37650558, 2023). "IL-7 blocks sepsis-induced lymphocyte apoptotic cell death by increasing the anti-apoptotic molecule Bcl-2." (PMID 36906875, 2023). "DNMT1-mediated inhibition of Bcl-2 expression promoted inflammation and apoptosis, contributing to myocardial injury in this LPS-induced sepsis model." (PMID 37947606, 2023). "On the other hand, negative stimuli such as cell injury can activate the PI3K/AKT/Bcl-2 pathway to suppress autophagy and exacerbate sepsis." (PMID 38161332, 2023). "In contrast, the transcript levels of anti-apoptotic genes, such as BCL2L11 and BCL2L1, were upregulated only in the sepsis group, wherein that of BCL2 was downregulated in both the groups." (PMID 36443881, 2022). "It was reported that the protein expression of Bcl-2 in peripheral blood was significantly decreased and cells were abnormally apoptotic during sepsis." (PMID 36699054, 2022). "Administration of naringenin, a commonly occurring flavonoid aglycone, at 10 and 20 mg/kg to sepsis rats model significantly decreased the sepsis-induced apoptosis of kidney cells, and also reduced Bax and raised Bcl-2 expression." (PMID 36588685, 2022). "In our study, menthol inhibited the sepsis-induced reduction of tissue Bcl2 levels, parallel to menthol-induced tissue protection and improved survival." (PMID 35814769, 2022). "As reported by other studies, menthol exhibited remarkable anti-apoptotic effects; it nearly eliminated the sepsis-induced elevation in hepatic cleaved caspase-3 and upregulated the anti-apoptotic marker, Bcl-2." (PMID 36120368, 2022). "We also observed that TXNIP knockdown upregulated the level of Bcl-2 and downregulated the cleaved caspase-3 and Bax levels in the hippocampus of sepsis mice, thereby inhibiting neuronal apoptosis." (PMID 35571246, 2022). "The percentage of blood T-lymphocyte and CD4+ T-cell populations was maintained in mice pretreated with Gln in the sepsis group, and the expression of the antiapoptotic Bcl-2 gene was more pronounced and increased in splenic CD4+ T cells." (PMID 36211442, 2022). "Upregulation of Bcl‐2 in rat lung tissues brought about reduced production of inflammatory cytokines and cell apoptosis in mice with sepsis‐induced lung injury." (PMID 35678255, 2022). "This study aims to investigate the molecular mechanism of long noncoding RNA (lncRNA) small nucleolar RNA host gene 1 (SNHG1)‐mediated DNA methyltransferase 1/B‐cell lymphoma‐2 (DNMT1/Bcl‐2) axis in sepsis‐induced myocardial injury." (PMID 35678255, 2022). "Firstly, Tregs are more resistant to sepsis-induced apoptosis, possibly because they display higher expression of Bcl-2, an anti-apoptosis protein, than other effector T cells." (PMID 33532141, 2021). "The T cell apoptosis mechanisms include upregulation of pro-apoptotic protein Bim and downregulation of anti-apoptotic protein Bcl-2, and Bcl-2 and Bcl-xL upregulation improves the prognosis in animal models of sepsis." (PMID 34335278, 2021). "Then, PQQ treatment rescued the reduction of Bcl-2 expression and elevation of Bax, Cleaved caspase-3 and Cleaved caspase-9 expression, alleviating sepsis-induced cell apoptosis of liver tissues." (PMID 34227919, 2021). "HOTAIR was reported to attenuate acute kidney injury in sepsis rats by targeting the miR-34a/Bcl-2 axis." (PMID 34126975, 2021). "an antiapoptotic effect by adjusting the balance between proapoptotic (bax) and antiapoptotic (bcl-2) proteins in favor of antiapoptotic (bcl-2) proteins to reduce sepsis-dependent cell death." (PMID 34499695, 2021).